HOTAIR (HOX transcript antisense RNA)
Diseases named in the same sentence as HOTAIR in open-access papers (continued):
Sharing a sentence is not in itself a finding about the gene and the disease.
multiple myeloma (5 papers, 2015 to 2023). "Of the lncRNAs discussed here, MALAT1 (in prostate cancer and multiple myeloma), HOTAIR (in NSCLC and multiple myeloma), and SPRY4-IT1 (in esophageal squamous-cell carcinoma) have been implicated as relevant biomarkers in liquid biopsies." (PMID 32244924, 2020). "Isin and colleagues reported that several circulating LncRNAs including TUG1, LincRNA-p21, MALAT1, HOTAIR, and GAS5 could be the potential biomarkers for diagnosis of chronic lymphocytic leukemia (CLL) and multiple myeloma (MM)." (PMID 26221732, 2015).
ovarian tumors (5 papers, 2017 to 2023). "In an ovarian tumor xenograft mouse model, HOTAIR downregulation inhibited tumor growth and cyclinD1 expression, and this inhibition effect was more remarkable when cisplatin was administered." (PMID 34660304, 2021). "Treatment of mice harboring platinum-resistant ovarian tumor xenografts with pHLIP-PNA constructs suppressed HOTAIR activity, reduced tumor formation and improved survival." (PMID 28420874, 2017). "In an ovarian tumor xenograft mouse model, downregulation of HOTAIR and ANRIL could slow down tumor growth." (PMID 34660304, 2021). "For instance, a peptide nucleic acid- based approach has been used to block the ability of lncRNA HOTAIR to interact with EZH2 and subsequently inhibit HOTAIR-EZH2 activity and resensitize resistant ovarian tumors to chemotherapy." (PMID 37232821, 2023). "In the current study, we describe a peptide nucleic acids (PNA)-based approach to block the ability of HOTAIR to interact with EZH2 and subsequently inhibit HOTAIR-EZH2 activity and resensitize resistant ovarian tumors to platinum." (PMID 28420874, 2017).
preeclampsia (5 papers, 2022 to 2024). Preeclampsia is a hypertensive disorder of pregnancy that is characterized by new-onset hypertension with proteinuria presenting after 20 weeks of gestation, and depending on mild or severe forms may initially present with severe headache, visual disturbances, and hyperreflexia. "In other disorders, the maternal and placental HOTAIR rs10783618 polymorphism conferred increased preeclampsia susceptibility." (PMID 35626352, 2022). "As noncoding RNAs are an important part of evolutionary genetics and have been confirmed to play regulatory roles in preeclampsia, seven lncRNAs reported to be associated with hypoxia were selected, including UCA1, EFNA3, H19, MALAT1, HOTAIR, FALEC, and HAS2-AS1." (PMID 36160709, 2022).
systemic sclerosis (5 papers, 2020 to 2023). A chronic disorder, possibly autoimmune, marked by excessive production of collagen which results in hardening and thickening of body tissues. "Overexpression of HOTAIR in systemic sclerosis dermal fibroblasts induces the transcription factor GLI2, leading to the pro-fibrotic phenotype." (PMID 36869839, 2023). "The increase in the number of myofibroblasts in vivo correlates with the disease severity of systemic sclerosis (SSc) and they display high levels of HOTAIR." (PMID 33540611, 2021). "HOTAIR induces GLI2 expression through Notch signaling in systemic sclerosis dermal fibroblasts." (PMID 35626352, 2022). "This provides a greater understanding of HOTAIR-mediated fibrosis in systemic sclerosis." (PMID 33303026, 2020). "In autoimmune diseases, the overexpression of HOTAIR in both systemic sclerosis (SSc) myofibroblasts and SSc skin biopsies correlates with a reduction in miRNA-34a expression and consequent Notch pathway activation." (PMID 37628760, 2023).
triple-negative breast carcinoma (5 papers, 2020 to 2025). An invasive breast carcinoma which is negative for expression of estrogen receptor (ER), progesterone receptor (PR), and human epidermal growth factor receptor 2 (HER2). "In the present study, we investigated the role of HOTAIR in cell migration and hypoxia-induced vasculogenic mimicry in triple negative breast cancer cells." (PMID 32466537, 2020). "In summary, our results suggest that HOTAIR inhibits cell migration and vasculogenic mimicry by targeting the miR-204/FAK axis in triple negative breast cancer cells." (PMID 32466537, 2020). "In summary, our results showed, for the first time, that HOTAIR mitigates cell migration and vasculogenic mimicry by targeting the miR-204/FAK axis in triple negative breast cancer cells." (PMID 32466537, 2020). "Here, we showed that HOTAIR has a pivotal role in hypoxia-induced vasculogenic mimicry in metastatic MDA-MB-231 and invasive Hs-578t triple negative breast cancer cells." (PMID 32466537, 2020). "In conclusion, our data suggested that HOTAIR inhibits cell migration and vasculogenic mimicry by targeting the miR-204/FAK axis in triple negative breast cancer cells." (PMID 32466537, 2020). "Moreover, in triple-negative breast cancer, lncRNA HOTAIR and MALAT1 play a synergistic role in promoting M2-like polarization of macrophages, and the simultaneous knockout of HOTAIR and MALAT1 can increase the expression levels of M1-like macrophage markers CD80 and MSLN." (PMID 37637063, 2023).
Alzheimer disease (4 papers, 2014 to 2024). A progressive, neurodegenerative disease characterized by loss of function and death of nerve cells in several areas of the brain leading to loss of cognitive function such as memory and language. "In this part, we elucidated important evidence for understanding the crucial roles of the HOTAIR functional network in signaling pathways and identifying new diagnostic biomarkers, as well as therapeutic targets for CNS disorders (e.g., ischemic stroke, Alzheimer’s disease (AD), PD, MS, and TBI)." (PMID 35813070, 2022). "To verify whether NEAT1, HOTAIR, and MALAT1 expression is also altered in Alzheimer’s disease, we quantified their levels by qRT-PCR in the temporal cortex, hippocampus, and cerebellum of the same AD patients and age-matched healthy controls which were analyzed in our previous work." (PMID 29997370, 2018).
bladder tumors (4 papers, 2020 to 2025). "Our current study from clinical bladder tumor samples indicates significant upregulation of ProT in bladder tumors compared with the corresponding adjacent normal tissues (p = 0.013) and a positive correlation between the expression levels of ProT and HOTAIR." (PMID 36471329, 2022). "Collectively, these results show that expression of ProT and HOTAIR is upregulated and positively correlated in clinical bladder tumor samples and cancer cell lines." (PMID 36471329, 2022). "Expression of ProT and HOTAIR was higher in bladder tumors than in normal adjacent tissues." (PMID 36471329, 2022).
coronary artery disease (4 papers, 2022 to 2024). "In humans, HOTAIR upregulation has been linked to congenital heart disease and HOTAIR polymorphisms have been linked to coronary artery disease." (PMID 36869839, 2023). "illustrated that HOTAIR rs4759314, rs1899663, and rs12826786 genotype combinations strongly affect coronary artery disease occurrence." (PMID 38958113, 2024). "In contrast, prior investigations have established a link between HOTAIR and MALAT1 with coronary artery disease and heart failure." (PMID 39172906, 2024).
diabetic cardiomyopathy (4 papers, 2020 to 2025). Diabetic cardiomyopathy is a disorder of the heart muscle in people with diabetes. "In diabetic cardiomyopathy, HOTAIR acts as a competing endogenous RNA (ceRNA) to increase SIRT1 expression by sponging miR-34a24." (PMID 38250607, 2024). "It has been reported that HOTAIR expression is reduced in myocardial tissues and serum of diabetic cardiomyopathy patients." (PMID 35207562, 2022). "Although HOTAIR has been considered as an oncogene in various types of cancers, it seems to possess a protective effect in patients with diabetic cardiomyopathy." (PMID 35207562, 2022).
endothelial dysfunction (4 papers, 2021 to 2025). In vascular diseases, endothelial dysfunction is a systemic pathological state of the endothelium (the inner lining of blood vessels) and can be broadly defined as an imbalance between vasodilating and vasoconstricting substances produced by (or acting on) the endothelium. "For example, we have shown in DR, that ANRIL regulates VEGF, H19 inhibits inflammatory responses and prevents endothelial dysfunction, HOTAIR promotes angiogenesis, oxidative stress and mitochondrial dysfunction, and MALAT1 regulates inflammation via modulation of epigenetic regulators." (PMID 40271126, 2025). "Therefore, HOTAIR is proposed as a suitable therapeutic target for UA nephropathy, providing a novel theoretical basis for developing new drugs and correcting endothelial dysfunction in a HUA environment." (PMID 34296520, 2021). "lncRNAs such as ANRIL, MEG3, HOTAIR, and MALAT1 regulate vascular smooth muscle cell proliferation, endothelial dysfunction, and angiogenesis in COPD." (PMID 39201688, 2024).
gastric cardia adenocarcinoma (4 papers, 2015 to 2025). A carcinoma that arises from glandular epithelial cells of the cardia of stomach. "Furthermore, although SNP rs12826786 of HOTAIR was related to gastric cardia adenocarcinoma risk, little evidence could support the genetic effects of HOTAIR SNPs on GC susceptibility and gene functions." (PMID 26384301, 2015).
gynecological cancers (4 papers, 2017 to 2025). "In the OV, UCEC, and CESC cohorts we analyzed, we identified HOTAIR as a lncRNA associated with all three gynecological cancer types." (PMID 40001977, 2025). "Studies investigating the relationship between HOTAIR and gynecological cancers have reported that in OV, HOTAIR interacts with PRC2 (Polycomb Repressive Complex 2) to suppress tumor suppressor genes." (PMID 40001977, 2025). "In gynecological cancers, HOTAIR aberrant expression has been involved in the oncogenic progression, lymph node metastases, and poor prognosis of EC." (PMID 34885213, 2021). "We further provide various perspectives on the association of some lncRNAs, i.e., HOTAIR, NEAT1, H19, MALAT1, and MEG3, in terms of invasion, proliferation, metastasis, apoptosis, and drug resistance of breast and gynecological cancers based on recent discoveries." (PMID 34885213, 2021). "Herein, we review the functional roles and clinical implications of HOTAIR in gynecologic cancers." (PMID 28649178, 2017). "In this review, we summarize the recent findings on the roles of HOTAIR in gynecologic cancers." (PMID 28649178, 2017). "Therefore, in this article, we highlight the role of various lncRNAs and specifically five lncRNAs—HOTAIR, NEAT1, H19, MALAT1, and MEG3—in cancers unique to women, including breast and gynecological cancers." (PMID 34885213, 2021). "In this article, we present a summary of the progress on ascertaining the biological functions of five lncRNAs (HOTAIR, NEAT1, H19, MALAT1, and MEG3) in female-oriented cancers, including breast and gynecological cancers, with the perspective of carcinogenesis, cancer proliferation, and metastasis." (PMID 34885213, 2021).
ischemic stroke (4 papers, 2019 to 2022). A stroke disorder caused by obstruction of blood flow to the brain, due to thrombotic (local blood clot formation) or embolic (due to a blood clot or other material traveling from another site) event. "In this review, we outline the mechanisms by which HOTAIR exerts its regulatory function and summarize its role in the pathogenesis of ischemic stroke, NDDs, MS, and TBI." (PMID 35813070, 2022). "However, the exact mechanism of HOTAIR involvement in ischemic stroke needs to be further clarified to develop targeted therapies for ischemic stroke." (PMID 35813070, 2022). "Altogether, these findings suggest that elevated HOTAIR expression may be involved in the pathogenesis of ischemic stroke, and silencing HOTAIR may play a therapeutic role in ischemic stroke through anti-inflammatory, anti-apoptotic, ceRNA, and other mechanisms." (PMID 35813070, 2022). "After matching ischaemic stroke-related lncRNAs with berberine-related lncRNAs, four genes (H19, HOTAIR, CASC2, and LINC00943) were selected as potential targets for berberine in the treatment of ischaemic stroke." (PMID 35815278, 2022). "Thus, it is speculated that HOTAIR may bind to NOX2, and HOTAIR silencing may be a treatment approach in ischemic stroke by downregulating NOX2 expression." (PMID 35813070, 2022).
mesothelioma (4 papers, 2018 to 2024). A usually malignant and aggressive neoplasm of the mesothelium which is often associated with exposure to asbestos. "In silico analysis of an existing TCGA dataset shows that for those samples showing overexpression of this lncRNA the majority were biphasic, and further analysis reveals that higher expression of HOTAIR in mesothelioma is associated with an poorer overall survival." (PMID 29701689, 2018).
metastatic melanoma (4 papers, 2013 to 2017). A melanoma that has spread from its primary site to another anatomic site. "Therefore, we next examined the ability of HOTAIR to affect cell motility using the scratch “wound” healing assays in human metastatic melanoma cell line A375." (PMID 23862139, 2013).
metastatic tumor (4 papers, 2016 to 2023). "HOTAIR expression is increased in both primary and metastatic tumors, and the expression level in primary tumors is a strong indicator of metastasis and mortality." (PMID 31319040, 2020).
Obesity (4 papers, 2020 to 2024). Accumulation of substantial excess body fat. "Specifically, elevated levels of HOTAIR have been observed in obesity, T2D, and DR, highlighting its potential as a valuable diagnostic and therapeutic target." (PMID 39765643, 2024). "SRA and HOTAIR can promote preadipocyte differentiation, and global knockout of SRA protects against HFD-induced obesity in mice." (PMID 36555704, 2022). "A group of lncRNAs including SRA, HOTAIR, adipogenic differentiation induced noncoding RNA (ADINR) and NEAT1 that are involved in the generation of white adipose tissue, are involved in the pathogenesis of obesity." (PMID 36555704, 2022).
pancreatic ductal adenocarcinoma (4 papers, 2017 to 2021). An infiltrating adenocarcinoma that arises from the epithelial cells of the pancreas. "HOTAIR expression was markedly increased in the pancreatic ductal adenocarcinoma (PDAC) cell lines and tissues, and HOTAIR silencing improved the radiosensitivity of PDAC cells via regulating the expression of Wnt inhibitory factor 1 (WIF-1)." (PMID 28376901, 2017). "Furthermore, the HOTAIR/miR‐206/TBX3 axis was shown to mediate cancer stemness of ovarian CSCs and pancreatic ductal adenocarcinoma CSCs express high levels of TBX3 and sustain stemness via an autocrine TBX3-ACTIVIN/NODAL signaling loop." (PMID 35145908, 2021).
type 2 diabetes (4 papers, 2016 to 2023). "HOTAIR may also affect type 2 diabetes mellitus (T2DM) susceptibility by modulating various signaling pathways." (PMID 37337955, 2023). "Compared to control subjects, expression levels of lncRNAs in PBMCs from type 2 diabetes patients showed significantly (p < 0.05) increased levels of HOTAIR, MEG3, LET, MALAT1, MIAT, CDKN2BAS1/ANRIL, XIST, PANDA, GAS5, Linc-p21, ENST00000550337.1, PLUTO, and NBR2." (PMID 30139387, 2018). "Compared to control subjects, expression profiling of lncRNAs in PBMCs from type 2 diabetes patients showed significantly (p < 0.05) increased levels of HOTAIR, MEG3, LET, MALAT1, MIAT, CDKN2BAS1/ANRIL, XIST, PANDA, GAS5, Linc-p21, ENST00000550337.1, PLUTO, and NBR2." (PMID 30139387, 2018). "A close correlation between circulating H19, HOTAIR, MIAT and SENCR levels was also observed in the type 2 diabetes group." (PMID 27874027, 2016).
acute leukemia (3 papers, 2019 to 2022). A clonal (malignant) hematopoietic disorder with an acute onset, affecting the bone marrow and the peripheral blood. "One of the best examples is HOTAIR, which is abnormally expressed in many cancer types, including acute leukemia, and consistently replicated across different cohorts." (PMID 35719952, 2022). "Many studies have demonstrated that HOTAIR expression was increased in several different types of cancers including breast cancer, lung cancer and acute leukemia." (PMID 34582651, 2021). "In addition, HOTAIR has been revealed to be correlated to upregulated Dnmt3a and Dnmt3b via the regulation of the DNA methylation in acute leukemia patients, contributing to the induced occurrence of acute leukemia." (PMID 31168296, 2019).
Arthritis (3 papers, 2021 to 2023). Inflammation of a joint. "HOTAIR-modulated changes in SF gene expression and function were associated with changes betweeen hand and knee arthritis in RA, suggesting that HOTAIR may shape the phenotype of arthritis in lower extremity joints." (PMID 38071204, 2023). "Here, we show that HOTAIR is a major regulator of site-specific gene expression in SF and modulates a series of highly relevant signalling pathways and SF functions in arthritis." (PMID 38071204, 2023). "In summary, these data support the notion that expression levels of HOTAIR in SF can shape the influx of immune cells in the synovium in arthritis and vice-versa." (PMID 38071204, 2023). "Downregulation of HOTAIR in an inflammatory environment led to activation of specific arthritis-relevant pathways and changes in SF function, which might modulate the arthritis phenotype in lower extremity joints." (PMID 38071204, 2023). "To determine which local factors could influence the expression of HOTAIR in arthritis, we assessed HOTAIR expression in SF upon stimulation by various cytokines and Toll-like receptor (TLR) ligands." (PMID 38071204, 2023).
astrocytoma (3 papers, 2015 to 2017). "Expression of HOTAIR has been found to differentiate between astrocytoma, oligodendroglioma, and/or oligoastrocytoma, suggesting its use as a potential biomarker in distinguishing morphologically similar cases." (PMID 29138748, 2017). "Moreover, we overexpressed the HOTAIR 3′ or 5′ domain in an astrocytoma-derived primary culture." (PMID 25823657, 2015). "Interestingly, introduction of the HOTAIR 5′ domain into an astrocytoma-derived primary culture dramatically decreased NLK expression, whereas the HOTAIR 3′ domain did not have this effect." (PMID 25823657, 2015).
Cirrhosis (3 papers, 2023 to 2025). A chronic disorder of the liver in which liver tissue becomes scarred and is partially replaced by regenerative nodules and fibrotic tissue resulting in loss of liver function. "Moreover, El-Khazragy and colleagues showed that HOTAIR may be a biological marker to predict the risk of developing HCC following DAAs (direct-acting antivirals) in HCV-related cirrhosis, allowing for the selection of patients at higher risk of developing HCC after DAAs treatment." (PMID 37240232, 2023).
colon adenocarcinoma (3 papers, 2021 to 2023). "HOXC11 positively regulates the lncRNA HOTAIR and is associated with poor prognosis in colon adenocarcinoma (COAD)." (PMID 36924407, 2023). "Although individual roles of these lncRs in RES’s anticancer effects are not clear, for example, downregulation of HOTAIR may be related to anticancer effects, since better disease-free survival rate was observed in colon adenocarcinoma patients with low HOTAIR expression." (PMID 36552560, 2022). "In colon adenocarcinoma HT-29 cells, the results of qRT-PCR indicated that RES decreased the expression of CCAT1, CRNDE, H19, HOTAIR, PCAT1, PVT1, and SNHG16, and upregulated CCAT2, MALAT1, and TUSC7." (PMID 36552560, 2022).
diffuse large B-cell lymphoma (3 papers, 2020 to 2023). "High expression of HOTAIR was observed in diffuse large B-cell lymphoma cells and correlated with chemoresistance." (PMID 34199840, 2021). "In addition, HOTAIR was thought to be involved in the resistance of diffuse large B-cell lymphoma to prednisone by regulating miR-130a." (PMID 34199840, 2021).
gouty arthritis (3 papers, 2022 to 2025). "In vivo experiments showed that HOTAIR knockout alleviated ankle swelling in a gouty arthritis mouse model." (PMID 41311848, 2025). "HOTAIR knockdown alleviates gouty arthritis through miR-20b upregulation and NLRP3 downregulation." (PMID 35626352, 2022).